PKD2L1 (polycystin 2 like 1, transient receptor potential cation channel)
Description:
Homotetrameric, non-selective cation channel that is permeable to sodium, potassium, magnesium and calcium. Also forms functional heteromeric channels with PKD1, PKD1L1 and PKD1L3. Pore-forming subunit of a heterotetrameric, non-selective cation channel, formed by PKD1L2 and PKD1L3, that is permeable to sodium, potassium, magnesium and calcium and which may act as a sour taste receptor in gustatory cells; however, its contribution to sour taste perception is unclear in vivo and may be indirect. The homomeric and heteromeric channels formed by PKD1L2 and PKD1L3 are activated by low pH and Ca(2+), but opens only when the extracellular pH rises again and after the removal of acid stimulus. Pore-forming subunit of a calcium-permeant ion channel formed by PKD1L2 and PKD1L1 in primary cilia, where it controls cilium calcium concentration, without affecting cytoplasmic calcium concentration, and regulates sonic hedgehog/SHH signaling and GLI2 transcription. The PKD1L1:PKD2L1 complex channel is mechanosensitive only at high pressures and is highly temperature sensitive. Pore-forming subunit of a calcium-permeant ion channel formed by PKD1L2 and PKD1 that produces a transient increase in intracellular calcium concentration upon hypo-osmotic stimulation (200 mOsm) (By similarity). May play a role in the perception of carbonation taste (By similarity). May play a role in the sensory perception of water, via a mechanism that activates the channel in response to dilution of salivary bicarbonate and changes in salivary pH (By similarity).
Synonyms: PKD2L; PKDL; TRPP3; PCL
Tractability: Small molecule: it belongs to a druggable protein family. Antibody: UniProt places it where antibodies can reach, with high confidence; its Gene Ontology location is reachable by antibodies, with high confidence; UniProt predicts a signal peptide or a membrane-spanning region; the Human Protein Atlas places it where antibodies can reach.
Gene: Protein-coding gene on chromosome 10 (100,288,149 to 100,330,264, reverse strand). Ensembl gene ENSG00000107593.
Subcellular location: Cell projection, cilium membrane; Cell membrane; Cytoplasmic vesicle
Subcellular location (Human Protein Atlas): Plasma membrane; Actin filaments; Cytosol
Gene Ontology:
Molecular function: alpha-actinin binding; calcium ion binding; calcium-activated cation channel activity; calcium-activated potassium channel activity; cytoskeletal protein binding; monoatomic cation channel activity; muscle alpha-actinin binding; pH-gated monoatomic ion channel activity; protein binding; sodium channel activity; calcium channel activity; identical protein binding; monoatomic cation transmembrane transporter activity; sour taste receptor activity; actinin binding; metal ion transmembrane transporter activity; osmolarity-sensing monoatomic cation channel activity; transmembrane transporter binding
Biological process: monoatomic cation transmembrane transport; potassium ion transmembrane transport; protein homotetramerization; sensory perception of sour taste; sodium ion transmembrane transport; transmembrane transport; cellular response to acidic pH; detection of chemical stimulus involved in sensory perception of sour taste; detection of chemical stimulus involved in sensory perception of taste; detection of mechanical stimulus; monoatomic cation transport; smoothened signaling pathway; calcium ion transmembrane transport; cellular response to pH; protein tetramerization; response to water
Cellular component: calcium channel complex; membrane; non-motile cilium; plasma membrane; cell surface; cytoplasmic vesicle; endoplasmic reticulum; receptor complex; cation channel complex; ciliary membrane
Genetic constraint (gnomAD): Loss-of-function variants: 66 observed, 80.78 expected, observed/expected ratio (o/e) 0.82, 90% interval 0.67 to 1. The upper end of that interval is the gene's LOEUF score, 1, which puts it in group 4 of 6, group 1 being the genes least tolerant of losing a copy. Missense variants: 887 observed, 949.47 expected, observed/expected ratio (o/e) 0.93, 90% interval 0.88 to 0.99. Synonymous variants: 368 observed, 374.09 expected, observed/expected ratio (o/e) 0.98, 90% interval 0.9 to 1.07.
Homologues: Orthologues: chimpanzee PKD2L1 (99% identical), macaque PKD2L1 (96% identical), dog PKD2L1 (91% identical), rabbit PKD2L1 (85% identical), mouse Pkd2l1 (82% identical), pig PKD2L1 (81% identical), guinea pig PKD2L1 (81% identical), rat Pkd2l1 (80% identical), tropical clawed frog pkd2l1 (64% identical), zebrafish pkd2l1 (55% identical). Paralogues in human: PKD2 (50% identical), PKD2L2 (36% identical), PKD1 (18% identical), PKDREJ (17% identical), PKD1L1 (15% identical), LOXHD1 (14% identical), DENND5B (13% identical), PKD1L3 (13% identical), DENND5A (12% identical), PKD1L2 (9% identical).
Diseases named in the same sentence as PKD2L1 in open-access papers:
PKD2L1 is named in the same sentence as 31 diseases in open-access papers, as found by Europe PMC text mining. Sharing a sentence is not in itself a finding about the gene and the disease. The quoted sentences say what the papers report.
polycystic kidney disease (9 papers, 2009 to 2022). A usually autosomal dominant and less frequently autosomal recessive genetic disorder characterized by the presence of numerous cysts in the kidneys leading to end-stage renal failure. "The polycystic kidney disease-like ion channel PKD2L1 and its associatedpartner PKD1L3 are potential candidates for sour taste receptors." (PMID 21625513, 2011). "Polycystic kidney disease (PKD) 2L1 [previously called polycystin-L or transient receptor potential (TRP) polycystin 3 (TRPP3) but renamed TRPP2] is a member of the TRP superfamily of nonselective cation channels." (PMID 22420714, 2012). "Interestingly, the sourness perception and thirst regulation occurred via the same acid-sensing receptor cell, which is called polycystic kidney disease 2-like 1 (PKD2L1) (Bichet, 2018;Gravinaet al., 2013)." (PMID 38433733, 2021). "The heteromeric complex between PKD1L3, a member of the polycystic kidney disease (PKD) protein family, and PKD2L1, also known as TRPP2 or TRPP3, has been a prototype for mechanistic characterization of heterotetrametric TRP-like channels." (PMID 34381056, 2021). "Another mechanism assumes that two members of the polycystic kidney disease (PKD) family of channels, namely, PKD1L3 and PKD2L1, are involved at least in part." (PMID 19812697, 2009). "In addition, PKD2L1 and PKD2 are also members of polycystins/polycystic kidney disease (PKD) proteins." (PMID 29567962, 2018). "The following transcripts were undetectable in the patients, even after 50 cycles of amplification, but readily detectable in the sour-normal subjects: acid sensing ion channels (ASICs) 1a, 1β, 2a, 2b, and 3; and polycystic kidney disease (PKD) channels PKD1L3 and PKD2L1." (PMID 19812697, 2009). "Although no mutations in the PKD2L1 gene have been identified in patients suffering from polycystic kidney disease to date and Pkd2l1 knock-out mice do not develop kidney cysts, polycystin-2L1 has attracted particular attention because it has been shown to act as a Ca2+ channel in primary cilia." (PMID 34345895, 2021).
cardiac hypertrophy (4 papers, 2020 to 2023). "PKD2L1-deficient mice exhibited aggravated pathological cardiac hypertrophy caused by a high salt diet, at the same time, less O2 consumption, reduced heat production and a decreased respiratory exchange ratio were also observed in mice with PKD2L1 mutation." (PMID 35118147, 2021). "PKD2L1 knockout leads to myocardial hypertrophy and fibrosis, reduces cardiac mitochondrial phosphorylation, and promotes mitochondrial calcium overload." (PMID 37507372, 2023). "Polycystic kidney disease 2-like 1 (PKD2L1), known to serve as an important sour sensor in taste cells, played possible roles in cardiac hypertrophy." (PMID 35118147, 2021). "PKD2L1 is also involved in high-salt-induced cardiac hypertrophy." (PMID 35051185, 2022). "PKD2L1 deletion results in increased acetylation of histone 3 lysine 27 in the sodium/calcium exchange 1 (NCX1) promoter, which ultimately promotes cardiac hypertrophy." (PMID 37507372, 2023).
polycystic kidney disease 2 (3 papers, 2019 to 2021). Autosomal dominant polycystic kidney disease caused by a mutation in PKD2. "CSF-cNs express the transient potential receptor channel 3 (Trpp3), further referred to as Pkd2l1 (for Polycystic kidney disease-2-like 1)." (PMID 31002663, 2019). "The polycystic kidney disease 1 and polycystic kidney disease 2–like proteins PKD2L1 and PKD1L3 have been identified as sour taste‐related receptors in human taste cells, and potential ion‐channel OTOP1 was present in taste cells in mouse that express Pkd2l1." (PMID 34401081, 2021).
Hypertension (2 papers, 2023 to 2025). The presence of chronic increased pressure in the systemic arterial system. "At the PKD2L1 locus, rs603424 showed strong evidence of a shared genetic signal with both hypertension and cholelithiasis, suggesting that this variant may drive both fatty acid composition and disease risk at this locus." (PMID 41024449, 2025). "Several loci were linked to cardiometabolic outcomes including type 2 diabetes, hypertension, and cholelithiasis, with functional evidence supporting gene–diet interactions at the PKD2L1 locus." (PMID 41024449, 2025).
lung squamous cell carcinoma (2 papers, 2024). "For lung squamous cell carcinoma, 11 genes were causally related, comprising COPA, NCSTN, U91328.19, GABBR1, IER3, HLA-DQB1-AS1, HLA-DQB2, ANKRD26, PKD2L1, PSMA4 and RAD51C." (PMID 38834983, 2024). "Five of the ten target drug genes are detected in lung squamous cell carcinoma tissues, whereas the expression of CCNA2, APOM, C4A, PKD2L1, and CYP21A2 was not very significant." (PMID 39175755, 2024).
Ageusia (1 paper, 2020). A rare condition that is characterized by a complete loss of taste function of the tongue. "In humans, two patients with sour taste ageusia have been reported and neither had detectable PKD2L1 transcripts, indicating a potential role of PKD2L1 in human sour taste." (PMID 33092534, 2020).
Anxiety (1 paper, 2023). Intense feelings of nervousness, tension, or panic often arise in response to interpersonal stresses. "PKD2L1−/− mice exhibit significant increased repetitive/stereotyped motor behaviors (marble burying), deficits in locomotor activity (open field), enhanced behavioral anxiety (zero maze), and reduced social interaction (three-chamber)." (PMID 37216541, 2023).
autism (1 paper, 2023). Persistent deficits in social interaction and communication and interaction as well as a markedly restricted repertoire of activity and interest as well as repetitive patterns of behavior. "Loss of PKD2L1 expression impairs ciliary maturation in mice, which behaviorally exhibits autism-like features and seizure susceptibility that may have implications to human neuronal ciliopathy conditions." (PMID 37216541, 2023).
coronary artery disease (1 paper, 2018). "While the comparison was done with Eastern Europeans, we identified significant signals in PKD2L1 and IL6R which are genes associated with taste and coronary artery disease, respectively." (PMID 30510563, 2018).
dental caries (1 paper, 2023). The decay of a tooth, in which it becomes softened, discolored, and/or porous. "PKD2L1 encodes a member of the transient receptor potential family of ion channels and is a potential candidate gene for the sour taste that detects acids in foods and drinks, which may influence dietary patterns and potentially influence dental caries." (PMID 36981009, 2023).
epilepsy (1 paper, 2023). A brain disorder characterized by episodes of abnormally increased neuronal discharge resulting in transient episodes of sensory or motor neurological dysfunction, or psychic dysfunction. "Although there are no reports associating human PKD2L1 variants with ASD or epilepsy, the neurophenotypic combination observed in PKD2L1 knockout mice reflects comorbidities presented in patient populations." (PMID 37216541, 2023). "Thus, while the direct genetic association of PKD2L1 with human neurodevelopmental diseases has not been reported, there is considerable precedent for loss of ion channel function altering neuron excitability and precipitating in epilepsy–ASD conditions." (PMID 37216541, 2023).
Kyphosis (1 paper, 2018). Exaggerated anterior convexity of the thoracic vertebral column. "Alizarin red staining of bony tissue confirmed that adult pkd2l1 mutant zebrafish exhibit an abnormal convex curvature of the spine and increased Cobb angle, phenomena consistent with kyphosis in humans." (PMID 30228263, 2018).
osteoporosis (1 paper, 2023). A condition of reduced bone mass, with decreased cortical thickness and a decrease in the number and size of the trabeculae of cancellous bone (but normal chemical composition), resulting in increased fracture incidence. "Six of these SNPs, mapping to WNT16, EN1, JAZF1, and PKD2L1, were genotyped among 631 patients evaluated for osteoporosis." (PMID 37831088, 2023). "Next, we analysed six selected SNPs in 631 patients evaluated for osteoporosis [rs2707518 (CPED1/WNT16), rs3779381 (WNT16), rs115242848 (LOC101927709/EN1), rs10239787 (JAZF1), rs603424 (PKD2L1) and rs6968704 (JAZF1)]." (PMID 37831088, 2023). "From this list, we selected the five SNPs with the lowest p-values for further analyses in patients evaluated for osteoporosis: rs2707518 (CPED1/WNT16), rs3779381 (WNT16, intron 1), rs115242848 (LOC101927709/EN1), rs10239787 (JAZF1, intron 2), and rs603424 (PKD2L1, intron 2)." (PMID 37831088, 2023).
retinal detachment (1 paper, 2011). An eye emergency condition which may lead to blindness if left untreated. "Within the genes identified, the expression of the major histocompatibility complex I gene HLA-C enables diagnosis of the disease, while PKD2L1 and SLCO4A1 -which are both down-regulated- act synergistically to provide an estimate of the duration of the retinal detachment process." (PMID 22174898, 2011).
Scheuermann disease (1 paper, 2023). A disorder characterized by osteochondrosis of the vertebral epiphyses in childhood. "Altogether, our results confirm that Pkd2l1-defective mutants develop a hyper-kyphosis of the thoracic spine that is exaggerated for males and therefore reminiscent of Scheuermann’s disease." (PMID 37016154, 2023). "Taken together, our results show that the phenotype of Pkd2l1-defective mutants evokes the sagittal imbalance observed in patients with Scheuermann’s disease." (PMID 37016154, 2023). "By applying orthopedic criteria to analyze the amplitude of the curvature at the apex of the kyphosis, the curve pattern, the sagittal balance and sex bias, we demonstrate that pkd2l1 knock-outs develop a phenotype reminiscent of Scheuermann’s disease." (PMID 37016154, 2023). "Based on these observations, we propose that the closest human pathology is Scheuermann’s disease and that the pkd2l1 knock-out is a relevant model for this idiopathic spine deformity." (PMID 37016154, 2023). "However, Scheuermann’s disease is diagnosed around the pubertal period and in young adults, making the onset of hyper-kyphosis in zebrafish pkd2l1 mutants distinct from that characterizing the human pathology." (PMID 37016154, 2023). "To test whether the phenotype of pkd2l1 mutants is reminiscent of Scheuermann’s disease, we used micro-computed tomography and performed an orthopedic analysis of the zebrafish spine based on the criteria allowing to define this pathology as such during the diagnosis process in patients." (PMID 37016154, 2023).
status epilepticus (1 paper, 2023). Status epilepticus is defined as a continuous seizure lasting more than 30 min, or two or more seizures without full recovery of consciousness between any of them. "Consistent with previous results, we find that PKD2L1−/− mice are significantly more prone to seizure events with faster first latency, total seizing time, and onset of status epilepticus (SE)." (PMID 37216541, 2023).
kidney disease (6 papers, 2008 to 2023). "The polycystic kidney disease 2-like 1 (PKD2L1) gene in genomic locus 49 was linked to 91 metabolites, including 3 named eicosanoids." (PMID 36837791, 2023). "Proteins related to TRP channels, including TRP-melastatin 5 (TRPM5), polycystic kidney disease-1-like 3 (PKD1L3), and polycystic kidney disease-2-like 1 (PKD2L1), are also expressed in taste cells." (PMID 31040368, 2019). "Polycystic kidney disease 2-like 1 (PKD2L1, also known as TRPP3) is an acid sensor in taste cells." (PMID 37507372, 2023).
kidney (4 papers, 2012 to 2023). "One of the important channels responsible for the sensory function is the polycystic kidney disease 2-like 1 (PKD2L1) channel." (PMID 37686387, 2023). "In situ hybridization showed expression of polycystic kidney disease 2-like 1 (PKD2L1) channels in dopaminergic CSF-c neurons." (PMID 35103591, 2022). "A syntenic analysis identified two copies of the sour taste receptor gene (polycystic kidney disease 2-like 1, pkd2l1) in both the YHS and Mariana hadal snailfish genomes." (PMID 33983934, 2021). "We performed qRT-PCR analyses to investigate mRNA expression of gustducin, TrpM5, NeuroD, SNAP25, and polycystic kidney disease 2-like 1 (PKD2L1)." (PMID 22536412, 2012).
cancer (1 paper, 2023). A tumor composed of atypical neoplastic, often pleomorphic cells that invade other tissues. "We evaluated the distribution of the TRP family in C1–C6 pan-cancer immune subtypes and observed that TRPC4, TRPC6, TRPM4, TRPV2, TRPV4, MCOLN1, and PKD2L1 had the potential to predict the immune subtype." (PMID 36830651, 2023).
cardiovascular disease (1 paper, 2022). "Similar to PKD2L1, transient receptor potential channels participate in the pathogenesis of cardiovascular disease." (PMID 35051185, 2022).
PKD2L1 also shares sentences with these, for which no sentence is quoted: infection (2 papers); bacterial infection (1); cholangiocarcinoma (1); cholelithiasis (1); diabetes (1); Kidney Cyst (1); prostate carcinoma (1); Renal cyst (1); retinal degeneration (1); tumor (1); type 2 diabetes (1).